MFN2 (mitofusin 2)
Diseases named in the same sentence as MFN2 in open-access papers (continued):
Sharing a sentence is not in itself a finding about the gene and the disease.
cancer (continued). "It indicates its promising therapeutic potential for cancer, supported by the observations that Mfn1 and Mfn2 expression in several different types of cancer was reduced." (PMID 41531728, 2026). "MFN2 expression was markedly reduced in various cancers and inversely correlated with PD-L1 levels and immunosuppressive gene signatures." (PMID 41896539, 2026). "In the cancer cell lines, expression of both MFN2 and DRP1 is significantly increased, while MFF expression is significantly lower in MDA-MB-231 cells compared to MCF7 cells." (PMID 39851508, 2025). "The reduction or dephosphorylation of Cav-1 can release Mfn2 and Drp1, promote mitochondrial dynamics and mitophagy, and reduce the accumulation of damaged mitochondria, thereby enabling cancer cell survival and affecting cancer treatment." (PMID 41030451, 2025). "Enhancing the interaction through the upregulation of MFN2 in CD8+ T cells has been shown to augment the effectiveness of cancer immunotherapy." (PMID 40661148, 2025). "In contrast, Leflunomide-mediated increases in MFN2 were only apparent in hepatocarcinoma liver samples and absent in control liver samples; Leflunomide restored MFN2 to baseline after a cancer-induced decrease." (PMID 38607070, 2024). "The role of MFN2 in cancer appears to be context-dependent, which varies with the types of cancer and the molecular alterations within tumor." (PMID 39430741, 2024). "The authors propose that MFN2 S200 phosphorylation in cancer tissues increases MFN2/Pyruvate kinase isoform 2 (PKM2) interaction, thereby favoring mitochondrial fusion and the switch between OXPHOS and glycolysis." (PMID 37627290, 2023). "MFN2 and ATP6V1E1 are two genes that associated with mitochondrial dynamics and metal ion transport, which were attribute to cancer development and chemoresistance." (PMID 37405988, 2023). "KAP1 Ser473 phosphorylation reduces MFN2 and mitochondrial hyperfusion, thereby inducing cancer cell survival." (PMID 36831455, 2023). "On a mechanistic level, this miRNA species has been found to induce mitochondrial dysfunction in skeletal muscle by targeting Mfn-2 but more studies are required in the context of cancer." (PMID 35454774, 2022). "Our studies have revealed that HITT directly interacts with MFN2 and increases mitochondrial fragmentation by preventing MFN2 homotypic or heterotypic complex–mediated mitochondrial fusion, thus sensitizing cancer cells to UV-induced cell death." (PMID 36567017, 2022). "As MFN2 exerts benefits for both the heart as well as for anti-cancer therapies, MFN2 is a potential therapeutic target for clinical translation." (PMID 35154486, 2022). "We suggest that MFN2 is a promising target for the treatment of anti-cancer medicine-induced cardiac dysfunction." (PMID 35154486, 2022). "When a miR-761 was inhibited, cancer cells were more receptive to apoptosis by upregulation of Mfn2." (PMID 35887244, 2022). "Subsequent demethylation with 5-aza-2′-deoxycytidine restored normal MFN2 expression and suppressed cancer growth and metastasis." (PMID 35887244, 2022). "It should be also noted that multiple functions of MFN2 have been identified, including the regulation of cancer metastasis and the immune response." (PMID 36567017, 2022). "The inhibition of cancer cell invasion by MFN2 overexpression was also confirmed in HTH83 cells (p < 0.001)." (PMID 33479369, 2021). "As a component of the outer membrane of mitochondria, MFN1/MFN2 can participate in cancer metastasis and cellular reprogramming of cancer stem cells." (PMID 33479369, 2021). "Conversely, cancer cell invasion was significantly reduced in MFN2-overexpressing Cal62 cells compared with that in control Cal62 cells (p < 0.001, c-ii)." (PMID 33479369, 2021). "It has been reported that mitochondrial fission is frequently increased in cancer cells due to the downregulation of the mitofusin proteins including Mfn1, Mfn2, and Opa1 and/or the upregulation of Drp1." (PMID 35582383, 2021).
cancer (continued). "Studies on breast, pancreatic, and lung cancer demonstrated that MFN2 inhibits cell proliferation or cancer progression through interact with RAS or suppression of phosphoinositide 3 kinase (PI3K)-protein kinase B (AKT) signaling." (PMID 33479369, 2021). "Previous studies suggested that MFN2 interact with RAS or suppresses cancer progression through inhibition of this signaling pathway in other cancers." (PMID 33479369, 2021). "A significant increase in Cal62 cancer cell invasion was observed after MFN2 KO compared with that in the controls (p < 0.001, a-ii)." (PMID 33479369, 2021). "One study showed that Mfn2 knockdown deregulated cell proliferation, cell cycle modulation, and invasion in cancer cells." (PMID 35582383, 2021). "Cancer cell migration was significantly accelerated in HTH83 cells when MFN2 expression was suppressed by siRNA (p < 0.001, d-ii)." (PMID 33479369, 2021). "Through the GEO database, we screened the differentially expressed circRNA in CRC tumor tissues and non-cancer tissues, and found that hsa_circRNA_100053 (circ-MFN2, also known as circ_0009910) was significantly upregulated in CRC tumor tissues." (PMID 34093664, 2021). "We detected the expression of circ-MFN2 in CRC tumor tissues and found that circ-MFN2 was markedly highly expressed in CRC tumor tissues compared to non-cancer tissues." (PMID 34093664, 2021). "Specifically, the low MFN2-expressing group was found to exhibit shorter cancer survival and poorer prognosis than the high MFN2-expressing group in breast cancer." (PMID 33479369, 2021). "Circ-MFN2 has been reported to be highly expressed in osteosarcoma, hepatocellular carcinoma, and gastric cancer, and can promote the development of cancer." (PMID 34093664, 2021). "Recent reports highlight the role of mitochondrial proteins Mitofusin-2 (Mfn2) and caseinolytic protease P (ClpP) in cancer progression." (PMID 34441434, 2021). "High expression of Mfn1, Mfn2 and OPA1 has also been linked to cancer cell proliferation, survival and invasion, while their inhibition blocks cell growth and triggers apoptosis of different cancer cells." (PMID 32244541, 2020). "While rather exacerbating damage caused by stress in healthy cells, compromising mitophagy and MFN2 lead to better disease prognoses in cancer." (PMID 33072754, 2020). "In fact, adenoviral expression of MFN2 showed an anti-tumor effect in vitro in a wide range of different cancer cell lines." (PMID 33072754, 2020). "Resveratrol up-regulates the expression of Mfn2 to stimulate mitochondrial fusion, leading to the decreased viability and proliferation of cancer cells." (PMID 32163546, 2020). "In sum, the pro-survival role of MFN2 and mitophagy in cancer cells suggest it as a potential target for inhibition in oncogenic treatments." (PMID 33072754, 2020). "As both knockdown and overexpression of Mfn2 impair cancer cell survival in certain cancer types, further studies need to further explore the different roles of Mfn2 in various tumor types." (PMID 31551926, 2019). "Since the phosphorylation-defective MFN2 mutants affect both OXPHOS and glycolysis, we evaluated the effect of WT MFN2 and mutants of MFN2 on the growth of H1299 cancer cells using cell proliferation assays and xenograft assays in nude mice." (PMID 30887444, 2019). "Together, these results show that phosphorylation of MFN2 affects cancer cell growth by promoting mitochondrial fusion and OXPHOS and suppressing glycolysis." (PMID 30887444, 2019). "In line with the lower Mfn2 expression in cancer, several studies demonstrate that Mfn2 overexpression inhibits cancer cell proliferation and colony formation and weakens the invasion and migratory ability." (PMID 31551926, 2019). "Mitofusin 2 (Mfn2) is involved in regulation of cell survival and has been of interest in cancer field." (PMID 31384172, 2019). "These ideas are supported by the results showing that both phospho-defective and phospho-mimic mutants of MFN2 suppress cancer cell growth." (PMID 30887444, 2019).
cancer (continued). "In a further set of experiments, we applied the same protocol which we used to characterize the different cancer cell lines to analyze the effects of Mfn2 knockout on energy metabolism." (PMID 30304688, 2018). "Our results highlight the concept that cotreatment of cisplatin and SFI prompted cell cycle arrest and mediated cell apoptosis events that were part of the upregulation of Mfn2, suggesting the role of Mfn2 in chemoresistance in cancer cells." (PMID 30410558, 2018). "This study reveals the critical contribution of MFN2 to suppress cancer progression through inhibition of mTORC2/Akt signaling and identifies mTORC2 as a potential therapeutic target for controlling tumor aggression." (PMID 28176801, 2017). "Conversely, cancer cells over-expressing mitofusin-2 show accelerated apoptosis, accompanied by increased ER-mitochondria Ca2+ flux." (PMID 28122638, 2017). "Our studies have identified MFN2 as a direct mTORC2 inhibitor in cancer cell lines in vitro and in vivo." (PMID 28176801, 2017). "Signaling analyses suggest the mammalian target of rapamycin complex 2 (mTORC2)/Akt signaling pathway is highly elevated in MFN2 knockout cancer cells." (PMID 28176801, 2017). "Additionally, previous research has demonstrated that MFN2 inhibits the growth and migration of other human cancer cells by regulating the epithelial-to-mesenchymal transition." (PMID 37405988, 2023). "Thus, unlike pulmonary vascular cells that rely primarily on mitochondrial OXPHOS for energy production, the Mfn2-overexpressing PAECs behaved like cancer cells and used glycolysis." (PMID 38139362, 2023). "Moreover, the activity of MFN2 is strictly tissue‐ and tumor‐specific and has completely different effects in different cancers." (PMID 36877954, 2023). "Intriguingly, MFN2 has been referred to as a tumor suppressor gene in some forms of cancer." (PMID 40396043, 2022). "On the contrary, MFN2 was known as a tumour suppressor and exhibited lower expression in cancers." (PMID 35044082, 2022). "In contrast, Mfn-2 has been found to inhibit the invasion and growth of lung and breast cancer." (PMID 35454774, 2022). "Considering that mTOR activators and NEC-1 (a necroptosis inhibitor) cannot be used in cancer therapy, we evaluated whether MFN2 exerted protective effects against sor-induced cardiac injury in vivo." (PMID 35154486, 2022). "Overexpression of MFN2 can effectively promote cancer cell apoptosis." (PMID 35154486, 2022). "Mitofusin-2, which reflects mitochondrial activity, was significantly increased in group 2, signifying that the degradation of muscle associated with cancer cachexia was significantly increased in group 2, but not in the NR-treated group." (PMID 34262449, 2021). "The modulation of PERK activity by Mfn2 at MERCs, in basal conditions, should be further investigated in cancer cells to understand whether Mfn2-dependent deregulation of PERK activity occurs at MERCs during carcinogenesis." (PMID 33842465, 2021). "We also evaluated cancer cell migration after modulation of MFN2 in these two cancer cell lines." (PMID 33479369, 2021). "MFN2 is also involved in cell cycle regulation, apoptosis, and differentiation, and it might play a role in cancer development." (PMID 33479369, 2021). "The expression of MFN2 was relatively higher in normal thyroid tissues than that in cancer tissues." (PMID 33479369, 2021). "Recently, MFN2 has also been shown to be an important regulator of cancer progression." (PMID 33479369, 2021). "Thus, dysregulation of MFN2 function as a tethering protein at the ER-mitochondria interphase is likely to participate in cancer progression." (PMID 33718356, 2021). "Conversely, MFN2 overexpression in cancer cell lines greatly inhibited cell migration and invasion." (PMID 33479369, 2021). "Recent studies indicated that Mfn2 has a key role in cancer progression; however, whether it acts as a tumors suppressor or oncogene in this process remains controversial." (PMID 34441434, 2021).
cancer (continued). "As shown in the MEF cell experiment, MFN2 might suppress cell proliferation in the other cancer cells." (PMID 33479369, 2021). "MFN2 is considered a tumor suppressor and is silenced in many malignant tumors." (PMID 33718356, 2021). "Consistent with our present findings of MIEF2 in OC, increased expressions of mitochondrial dynamic proteins such as DRP1 (dynamin related protein 1), mitofusin 1 (MFN1) and mitofusin 2 (MFN2) have also been reported in human cancers of liver, lung, colon and breast." (PMID 33317572, 2020). "Mitochondrial fission and MFN2 downregulation are often found in various cancer cells." (PMID 33052246, 2020). "The role of mitofusin 2 in controlling cell proliferation possibly explains its link with cancer." (PMID 33072754, 2020). "Some cancer cells exhibit high levels of mitochondrial fission and have associated decreases in respiratory capacity as mediated by an imbalance of dynamin-related protein 1 (DRP1) and mitofusin-2 (Mfn2)." (PMID 30694178, 2019). "Both the S200A and S200E mutants of MFN2 partially restored cancer cell growth." (PMID 30887444, 2019). "In addition, the proliferation of various cancer cell lines also proved sensitive to Mfn2 knockdown." (PMID 30694178, 2019). "Furthermore, we show that MFN2 negatively regulates cancer cell survival through inhibiting mTORC2 and Akt." (PMID 28176801, 2017). "Future studies of a role of MFN2 in tumor suppression, especially in the context of activation Akt, may prove informative for the understanding and therapeutic strategy against cancer." (PMID 28176801, 2017). "Since normal apoptosis progression requires a functional MAM, understanding its role in cancer may provide clues as to what function mitofusin-2 performs for the MAM." (PMID 28603693, 2017). "Like MAPK, Mfn2 antagonism of Akt would be disadvantageous for cancer cell survival." (PMID 28513539, 2017). "MFN2 role in cancer is still controversial, acting either as an onco-suppressor or oncogenic factor, depending on the tumour type and the tissue; however, in many solid tumours, MFN2 shows an anticancer function, inducing cell apoptosis and inhibiting proliferation through Bax-mediated apoptosis." (PMID 40274776, 2025). "To address this, we analyzed downstream targets of MFN2 using Western blot analysis, revealing that the combination of circTAF4B shRNA and MFN2 siRNA distinctly suppressed phosphorylated AKT, suggesting that circTAF4B shRNA might exert anti-cancer effects through MFN2-mediated AKT signaling." (PMID 39430741, 2024). "Depletion of MARCH5 in those cancers could help raise the levels of MFN2 and strengthen its effect." (PMID 38139010, 2023). "Moreover, monitoring MARCH5 levels in the same cancer could be a prognostic indicator because an increase in the levels of MARCH5 would negatively reflect on the protein levels of MFN2, and vice versa." (PMID 38139010, 2023). "MFN2 could suppress cancer progression by inhibiting mTORC2/Akt signaling." (PMID 36531021, 2022). "Thus, HITT inhibits MFN2 homodimerization or heterodimerization in cancer cells." (PMID 36567017, 2022). "Notably, recent research has also demonstrated that restoration of the fused mitochondrial network—through either DRP1 knockdown/inhibition or MFN2 overexpression—impairs cancer cell growth, suggesting that mitochondrial network remodeling is essential in cancer progression." (PMID 34830966, 2021). "However, studies on the effect of Mfn2 on chemotherapy resistance in cancer are very limited." (PMID 35582383, 2021). "Indeed, MFN2 overexpression is able to slow the growth of different cancer cell lines." (PMID 33072754, 2020). "To explore the hypothesis that dysregulated mitochondrial dynamics may impact drug sensitivity, we began by examining the alteration status of six canonical dynamics-regulating genes - OPA1, MFN1, MFN2, FIS1, MFF, and DNM1L (which encodes Drp1)—in human cancers." (PMID 29700304, 2018).
cancer (continued). "Furthermore, MFN2 acts as a tumor suppressor in diverse cancers of the bladder, stomach, and lung." (PMID 27389277, 2016). "The phosphorylation-dependent interaction of scaffolding protein caveolin-1 (Cav-1 Y14) inhibits the entry of Mfn2 and Drp1 to the mitochondria and the creation of the PINK1/Mfn2/Parkin complex in cancer cells." (PMID 40148800, 2025). "Similarly, in weight stable Apc(min/+) mice, mitochondrial mRNA for Pgc‐1α, Pparα, and Mfn2 were significantly decreased in quadriceps, indicating that mitochondrial biogenesis is impacted prior to obvious body and muscle wasting in the development of cancer cachexia." (PMID 40985218, 2025). "In contrast to mitochondrial fusion molecules, MFN1 and MFN2 exhibit tumor-suppressing roles in cancer, and deletion of MFN1/2 promotes tumor growth and malignancy, whereas overexpression of MFN2 results in significant tumor reduction in vitro and in vivo." (PMID 36831455, 2023). "Extensive genes have been identified as the target of miR-761 in numerous cancers, including HDAC1, Rab3D, Runx3, Mitofusin-2, CXCR1, TRIM29, MSI1, ING4, TIMP2, and GSK3β." (PMID 32185226, 2020). "Having observed little MFN-1 modulation in response to DxR, MFN-2 was selected to inhibit mitochondrial fusion and OXPHOS, both of which have roles in chemo-resistant cancers." (PMID 33204855, 2020). "Resveratrol induces mitochondrial fusion and fission via Mfn2 upregulation and PKM2 down-regulation, respectively, leading to reduced viability and proliferation of cancer cells via cell cycle arrest." (PMID 32163546, 2020). "In summary, our study reveals a novel signaling axis composed of mTOR, MFN2 and PKM2, which controls the metabolic switch between glycolysis and OXPHOS for cancer cell growth." (PMID 30887444, 2019). "In summary, these data show that Mfn2 ubiquitylation and p62 recruitment to mitochondria take part in PINK1/Parkin-mediated mitophagy in B5G1-treated resistant cancer cells." (PMID 30850585, 2019). "From these functions, and if restricting a cancer role to its function on the MAM, we would predict that PERK, like PACS-2 and mitofusin-2, should act as a tumor suppressor." (PMID 28603693, 2017). "In particular, reduced protein expression levels of Mfn1, Mfn2, and Opa1 and high levels of Fis1 and DLP1/ Drp1 were observed in certain cancer conditions." (PMID 28402939, 2017). "Our results suggest that ERRα elevated Mfn-1 and Mfn-2 to induce EMT, resulting in cancer cell migration." (PMID 27966445, 2017). "Among the cancer-specific targets of the isomiR, we highlight FBXO31 and MFN2." (PMID 36688696, 2023). "Because also mitochondrial fusion genes appear to be amplified in the same cancers, we wished to investigate whether levels of the three fusion mediators OPA1, MFN1 and MFN2 were upregulated across cancer types." (PMID 35279198, 2022). "Recently, Mfn2 has attracted much attention in cancer studies, but its exact role is not well established." (PMID 35582383, 2021). "These suggested that circ-MFN2 might have a pro-cancer role in CRC, which was similar with the function of circ-MFN2 in other cancers." (PMID 34093664, 2021). "It has been reported that MFN1 gene expression was decreased in animals with cancer cachexia, although no consensus has been established for MFN2 in the same context." (PMID 31466311, 2019). "We find that MFN2 knockout from MCF7 and A549 cells via Crispr/Cas9 greatly promotes cell viability, colony formation, and invasion of cancer cells in vitro and in vivo, which were confirmed by colony formation assay, transwell invasion assay, and tumor xenograft model." (PMID 28176801, 2017). "Together, these observations indicate that mitofusin-2 is a factor in cancer that typically results as reduced or absent in the cancer scenario." (PMID 28603693, 2017).